CD274 (CD274 molecule)
Diseases named in the same sentence as CD274 in open-access papers (continued):
Sharing a sentence is not in itself a finding about the gene and the disease.
tumor (continued). "To confirm the hypothesis and realize more effective treatment and inhibition immune evasion of CTCs, we selected mice tumor 4T1 cells as a CTC model, and blocked two immune checkpoints: CD47 and CD274." (PMID 30872703, 2019). "In view of these interesting observations from this and other studies, it is plausible that CD274 may work with its related molecule, e.g., CD80, in triggering acute phase liver graft injury and post-transplant tumor recurrence." (PMID 29642405, 2018). "Worth noting was the expression of the inhibitory immune checkpoint programmed death ligand 1 (CD274—best known as PD-L1), induced by IFN-γ produced by activated immune cells, including NK cells, which constitutes a prominent mechanism of tumor “adaptive resistance” to immunosurveillance." (PMID 30597841, 2018). "Recently, the TIME (Tumor Immunity in the MicroEnvironment) classification system was developed based on high/low levels of tumor CD274 (PD-L1) expression and presence/absence of TILS to classify cancer subtypes." (PMID 30071442, 2018). "Paradoxically, our data suggest that ionizing irradiation may induce multiple resistance mechanisms that could facilitate tumor relapse, e.g. via enhancing CXCL12 and also CD274/CD279 (PD-L1/PD-1) signaling, thus limiting anti-tumor immunity." (PMID 28423491, 2017). "Cell surface expression of the checkpoint protein programmed death ligand 1 (PD-L1, also named B7-H1 and CD274) is a potent mechanism of immune evasion employed by a wide variety of tumor types and is the target of several checkpoint blockade immunotherapies for cancer." (PMID 29181416, 2017). "CD274 (PD-L1) expression was observed in inflammatory cells in tumor stoma, but not in tumor cell in the present study." (PMID 29108360, 2017). "However, the IR tumours also had high expression of the negative regulators of immune response PDCD1 (PD-1), CD274 (PD-L1) and CTLA4 (CTLA-4)." (PMID 26729235, 2016). "PD‐L1, also known as B7‐H1 and CD274, belongs to the B7 costimulatory family; and is expressed in macrophages, DCs, immune cells including activated T cells and B cells, epithelial cells and tumour cells." (PMID 27241533, 2016). "For example, tumor cells can express programmed death receptor ligand 1 (PD-L1, CD274, B7-H1), a member of the B7-family of co-stimulatory molecules, that acts as a co-inhibitory molecule for T cells by binding the programmed death receptor 1 (PD-1) upregulated on activated T cells." (PMID 23383287, 2013). "However, a single-cell study revealed that one IRF8+NR1H2 macrophage cluster and another CD274 cluster exhibited similar gene expression and were similar to M1 macrophages during the anti-tumor immune response of early-stage OC, and IRF8 and CD274 were upregulated in an activation-dependent manner." (PMID 41601649, 2026). "It was interesting that CD274 was expressed to a lower degree in the higher DEG score group and we speculated that PD-L1 was highly expressed in tumor tissue in the lower DEG score group, which contributed to tumor immunoescape mechanisms and could lead to a poor prognosis." (PMID 41142609, 2025). "Consistently, lacidipine treatment or co‐administration with DOX/cisplatin significantly increased the mRNA expression of CCL5, CD274, CXCL10, and CXCL11 and decreased CCL2 mRNA levels in tumor tissues, thereby promoting immune cell infiltration and converting the “cold” into a “hot” tumor." (PMID 39585774, 2025). "Tumor stage and CD274 expression were not correlated with the FAM114A1 level." (PMID 41249116, 2025). "Interestingly, while succinylation levels were elevated in tumor-proximal immune cells, overall succinylation scores in CRC showed a negative correlation with the expression of immune checkpoint molecules such as PDCD1 (PD-1), CD274 (PD-L1), and CTLA4." (PMID 40463370, 2025).
tumor (continued). "Interestingly, tumor BECs also express a variety of immunosuppressive receptors, such as FasL, CD73, VACM-1, and programmed cell death ligand 1 (PD‐L1, CD274), which are involved in impeding the infiltration of immune effector cells in the adjoining tissue around the vessel." (PMID 40809013, 2025). "For example, increased immune infiltration associated with high gene expression might not be causally mediated by PSD3, CD274, or TNFSF18, but rather reflect a broader inflammatory state of the tumor." (PMID 40895529, 2025). "In particular, the study observed the upregulation of multiple immune evasion-related genes, including PD-L1 (CD274), HLA class I molecules (HLA-A/B/C), and β2-microglobulin (B2M), suggesting that IFN γ may influence its antitumor effects by modulating tumor cell immune escape mechanisms." (PMID 40805243, 2025). "Additionally, PD-1 interacts with its ligands, programmed death-ligand 1 (PD-L1) (B7-H1; CD274) and programmed death-ligand 2 (PD-L2) (B7-DC; CD273), which are expressed on antigen-presenting cells (APCs) and, in some cases, tumor cells to mediate immunosuppression." (PMID 40149458, 2025). "Furthermore, FAM114A1-low patients presented significantly greater CD8+ T-cell infiltration, independent of tumor stage, and CD274 and PDCD1 expression, according to multivariate logistic regression analysis." (PMID 41249116, 2025). "Second, tumor subsets enriched for microenvironment features, including hypoxia markers (e.g., Slc2a1, Pdk1, Car9), extracellular matrix (ECM) genes (e.g., Matn2, Fn1, Dcn, Col6a1), vasculature (e.g., Cdh5, Pecam1, Vwf), and interferon response genes (e.g., Rsad2, Ifit3, Gbp3, Cxcl10, Cd274)." (PMID 40171265, 2025). "Our mechanistic study revealed that TBC1D1-mediated inhibition of CTL function could be attributed to the upregulation of various immune checkpoint molecules, including ARG1, CD68, PDCD1, CD274, TGFB1, and CTLA4, collectively impeding the anti-tumor immune response." (PMID 38529286, 2024). "Additionally, immune checkpoint molecules (e.g., CCR4, CD27, CD274, CD68, CTLA4, PDCD1, and PDCD1LG2) were significantly upregulated in the AERShigh group (all p < 0.01), suggesting potential impairment of the anti-tumor immune response." (PMID 39464883, 2024). "Therefore, we investigated the evolutionary history of cancer associated gene sequences across 384 mammalian taxa, to detect signatures of selection across categories of oncogenes (GRB2, FGL2 and CDC42), tumour suppressors (LITAF, Casp8 and BRCA2) and immune genes (IL2, CD274 and B2M)." (PMID 38773187, 2024). "Within these potential markers, CD274 (also named PDL1) is a special gene both identified by our method as NA PCOS specific gene and reported to be related to immunity and inflammation, and might indicate important implications between NA PCOS and tumor." (PMID 38347589, 2024). "In addition, the expression of immune checkpoint proteins such as PD1 and PD-L1/CD274 are not restricted to MSI tumours." (PMID 38040818, 2024). "Besides PD-1, the expression of PD-L1 (B7-H1, CD274)/L2 (B7-DC, CD273) is detected in TAMs, which induce CD8+ T cells anergy and apoptosis through PD-1 binding on the surface of CD8+ T cells to inhibit anti-tumor immune response." (PMID 38957393, 2024). "Key tumour–non-cancerous cell interactions include the PD-L1/PD-1 (CD274/PDCD1) and Galectin-9/TIM-3 (LGALS9/HAVCR2) pathways, which are significantly upregulated in Low TPS and show a negative correlation with TPS, indicating the influence of the tumour microenvironment (TME)." (PMID 39457550, 2024). "Unlike in BMDMs, IL-17A did not induce Cd274 upregulation in tumor cells." (PMID 36239683, 2023). "Additionally, in vitro, the USP8 inhibitor-αPD-L1 combination therapy did not significantly improve the killing of tumor cells by activated T cells in Cd274 KO KPC cells compared to parental KPC cells." (PMID 36539510, 2023).
tumor (continued). "Importantly, the tumor immune dysfunction and exclusion (TIDE) algorithm showed that in CCL2-high GBM group, the expression of CD274, CTLA4, HAVCR2 and other immune checkpoints were significantly increased, and the immune checkpoint blockade (ICB) therapy was accordingly more responsive." (PMID 38057698, 2023). "PD-L1 IHC staining on tumor cells and/or tumor-infiltrating lymphocytes (TILS) is currently the gold standard eligibility assessment for ICB treatment, but its concordance with expression levels of the gene encoding PD-L1 (CD274) is not well established." (PMID 35881197, 2023). "Moreover, KLRB1 expression exhibited a positive correlation with the expression of PDCD1 (r = 0.624), CD274 (r = 0.317), and CTLA4 (r = 0.541) under condition of tumor purity, and PDCD1 (r = 0.731), CD274 (r = 0.441), and CTLA4 (r = 0.643) under condition of age in BRCA." (PMID 37988189, 2023). "The expression of PD-1 is induced on effector T-cells in response to inflammatory signals, and PD-L1 (B7-H1 or CD274) was the first identified ligand of PD-1 and is expressed in lymphocytes, vascular endothelium, mesenchymal stem cells, neuronal cells, and tumor cells." (PMID 36836455, 2023). "Interestingly, this immature neutrophil population had the lowest expression of PD-L1 (CD274) among all neutrophil subsets identified and could, if expanded, represent an interesting mechanism to stimulate anti-tumour immunity." (PMID 37534829, 2023). "In desmoplastic tumor samples, the expression of CD274 is significantly increased compared to non-desmoplastic tumor samples, suggesting that CRCLM patients with desmoplastic growth patterns should benefit from therapy with an immune checkpoint inhibitor for PD-L1." (PMID 37370832, 2023). "The B7 immune checkpoint superfamily includes B7-1 (CD80), B7-2 (CD86), B7-H1 (PD-L1, CD274), PD-L2 (PDCD1LG2), B7-H3 (CD276), B7-H4 (B7-x, VTCN1), and the inducible costimulator ligand (L-ICOS, CD275), which act as ligands on the surface of tumor cells or antigen-presenting cells." (PMID 36983005, 2023). "The authors suggested that the group with high CD274 expression on tumor and immune cells and with high levels of tumor-infiltrating cells could benefit from immunotherapy, compared to CD274 negative and with low immune cells CRC." (PMID 36013315, 2022). "In contrast, levels of CD274 (PD-L1) and PD-L2 transcripts are elevated in GBM-interacting microglia, suggesting that genes involved in immunologic tolerance are up-regulated in microglia by GBM contact, resulting in indirect inhibition of anti-tumour functions of T cells." (PMID 36555253, 2022). "Thus, poorly infiltrated tumours do not necessarily require high CD274 expression for immune escape." (PMID 35802807, 2022). "Furthermore, defective expression of MHC molecules may lead to tumor immune evasion or resistance to ICB therapy, we found that CD274 and PDCD1LG2 were globally correlated with several immunosuppressive molecules, MHC molecules, and chemokines across cancers." (PMID 36276934, 2022). "Cancer cells overexpress the programmed death-ligand 1 (PD-L1), which binds to the programmed death-1 receptor (PD-1 or CD274) on activated T cells delivering an inhibitory signal to cytotoxic T lymphocytes that prevents tumor elimination from the immune system." (PMID 34201050, 2021). "One of the ligands of PD-1 is PD-L1 (also known as CD274 and B7-H1), which is expressed by all hematopoietic cells, many nonhematopoietic cells (such as endothelial, epithelial, and mesenchymal stem cells), as well as many tumour cells." (PMID 34063096, 2021).
tumor (continued). "Along with its ligands PD-L1 and PD-L2, also known as CD274 and CD273, PD-1 plays an important role in maintaining self-tolerance and is often involved in immune escape in cancer by inhibiting the direct cytotoxic activity of effector CD8-positive T cells on tumor cells." (PMID 33669431, 2021). "In addition, in order to confirm whether VEC-PD-L1 had a role on the efficacy of anlotinib, we injected bEnd.3 (−) or CD274-bEnd.3 (+) cells intratumorally into tumor tissues separately with anlotinib treatment." (PMID 32366856, 2020). "Thus, tumor cells may express CD80/86 to suppress T cell activity via binding to CTLA4, or express PD-1 ligands PD-L1 (CD274) or PD-L2 (PDCD1LG2, PD-2 ligand)." (PMID 32903482, 2020). "Interestingly, PD-1 (gene symbol, PDCD1) and PD-L2 (gene symbol, PDCD1LG2), but not PD-L1 (gene symbol, CD274), are included in this global immune gene signature, likely because PD-L1 was expressed in intraepithelial immune cells, but not in tumor cells." (PMID 30956779, 2019). "For several decades, efforts have been made to improve the prognostic classification of STSs; different tumor cell‐intrinsic molecular parameters have been proposed, mainly related to cell cycle such as CINSARC, as well as parameters related to immune microenvironment, such as PDL1/CD274 expression." (PMID 31131495, 2019). "However, we did not observe a significant difference in expression of Cd274 on Epcam+ cells from normal lungs compared to cells from tumor bearing or erlotinib treated lungs." (PMID 31291990, 2019). "PD-1 can bind two ligands from the B7 protein family: PD-L1 (B7-H1, CD274) expressed by macrophages, DCs, activated T and B cells, tumor cells, and tissues, such as heart, lung, spleen and PD-L2 (B7-DC, CD273), which is mainly expressed on DCs and tumor tissues." (PMID 32039024, 2019). "Thus, both CD47 and CD274 proteins contribute to the tumor micro-environment by affecting T cell activation and angiogenesis, and the results confirmed that the percentage of T cells and NK cells were increased with the blockade of CD47 or/and CD274." (PMID 30872703, 2019). "In addition to its general immunoregulatory functions, CD274 is also involved in tumorigenesis, as reflected by its high expression level in tumor tissues rather than in adjacent non-tumor tissues of various cancers." (PMID 29642405, 2018). "Programmed cell death ligand 1 (PD-L1, also known as B7-H1 or CD274) is believed to mediate local immune evasion in many types of cancer by binding to programmed cell death 1 (PD-1), its co-stimulatory receptor on T cells, to induce saturation of activated anti-tumor T cells." (PMID 29291717, 2018). "The tumor-inducing effect of CD274 may also involve other immunoregulatory molecules, such as CD80, whose intragraft gene expression level correlated positively with CD274 in transplant recipients as reported here." (PMID 29642405, 2018). "In contrast to CTLA-4, PD-1 acts via interactions with its ligands PD-L1 (also known as B7-H1 or CD274) and is involved mainly in T cell activity modulation in peripheral tissues as well as providing a major immune resistance mechanism within the tumor microenvironment." (PMID 28866656, 2018). "In combining results of bioinformatics analyses and validation assays, tumor-related genes such as NNMT, FLI1, GAS6, lncRNA CCAT1, PDCD1LG2, and CD274 may be considered as the key regulators in tumor-like transformation in response to long-time exposure of P. gingivalis." (PMID 28286742, 2017). "The mechanism how CD274 (PD-L1) worked on radiation response would be investigated in the further studies including post-PCRT tumor evaluation We did not analyze prognosis according to immune infiltrates which have been mainly studied in the previous literatures." (PMID 29108360, 2017).
tumor (continued). "CD274 (programmed death ligand 1, also known as B7H1) is expressed in both solid tumors and hematologic malignancies and is of critical importance for the escape of tumor cells from immune surveillance by inhibiting T cell function via its receptor, programmed death 1 (PD-1)." (PMID 27855694, 2016). "With regard to the origin of sPD-L1, its plasma concentration was significantly correlated with CD274 expression in whole blood, but was not correlated with CD274 expression in tumor tissue or with tPD-L1 expression, indicating that sPD-L1 in plasma might be derived predominantly from blood cells." (PMID 38557498, 2024). "In addition, interference with the expression of RAP2C-AS1 suppresses the proliferation and migration of BLCA cells, and RAP2C-AS1 could affect the expression of CD274 and CTLA4, which could serve as prognostic markers and characterize the tumor microenvironment in BLCA." (PMID 38071230, 2023). "Although they are not strongly correlated with tumor mutation burden (TMB) or microsatellite instability (MSI), ADIPOR1/2 genes display a significant association with cancer stemness, tumor immune microenvironment, immune checkpoint genes (especially CD274 and NRP1), and drug sensitivity." (PMID 36896172, 2023). "Interestingly, FDX1 was significantly negatively correlated with the expression of many immune checkpoint genes in ACC, especially PD-1 (PDCD1), PD-L1(CD274), CTLA4 and other important immunotherapy targets, which may also be closely related to the immune escape mechanism of ACC tumor cells." (PMID 35991547, 2022). "Besides, aberrant amplification or deletion event associated with immune checkpoint stimulator genes (CD247, CD274, PD-1, PD-L1, and LAG3) was observed in distinct subgroups, upregulation of which expression could restrict anti-tumor response and facilitate immune escapes." (PMID 33407498, 2021). "In addition, we found that key immune-checkpoint inhibitors and their ligands such as PD1-PDL1 (CD274) and CTLA4-CD80/86 had higher interaction score in tumor than that in normal samples, in concordant with our above observation that both CD4 and CD8 T cells were more exhaustive in tumor samples." (PMID 34921160, 2021). "Additionally, LAMP3+ DCs showed the highest level of CD274, which was even higher than what was observed in Tregs from BC tissues, indicating that this DC subgroup could inhibit CD8+ T cells directly or via recruiting Tregs into the tumor region." (PMID 33033240, 2020). "In addition, CD274 promoter methylation significantly correlated with PDCD1 methylation, suggesting that epigenetic regulation of the PD-1 receptor may be paralleled by PD-L1 induction in tumor tissue." (PMID 28487502, 2017). "In contrast, both CD274/PD-L1 copy number status and PD-1 immunohistochemical expression were found to be not relevantly correlated with the presence of nodal metastases and were also not relevantly correlated with age, gender, grading, tumor size, or HPV-positivity." (PMID 26918453, 2016). "While the marker of proliferation, MKI67, was increased in tumor samples, DIPG tumor samples showed no significant upregulation of immune checkpoint markers PD-L1 (CD274) and CTLA-4 compared to matched normal tissue." (PMID 41541220, 2026). "In NEPC samples, canonical immune checkpoint genes PDCD1, CD274 and PDCD1LG2 were absent, while CD276 was uniformly expressed across tumour regions." (PMID 40677104, 2025). "In TNBC, PD-L1 expression is not merely correlated with but can be directly driven by a tumor-intrinsic CD28-SNRPB2 pathway, which stabilizes Cd274 mRNA." (PMID 41567982, 2025). "CD274 expression was found to be down-regulated in tumor tissues (P < 0.05), while TIGIT, PDCD1, CTLA4 and LAG3 expression in tumor tissues were not statistically different." (PMID 36959799, 2023). "A decreased expression of CD274 and CCR6 (p < 0.001) on non-hematopoietic cells from tumor samples when compared with non-tumor samples was observed." (PMID 37370832, 2023).